TFAP2A (transcription factor AP-2 alpha)
Diseases named in the same sentence as TFAP2A in open-access papers (continued):
Sharing a sentence is not in itself a finding about the gene and the disease.
ovarian carcinoma (7 papers, 2010 to 2024). A malignant neoplasm originating from the surface ovarian epithelium. "The expression of TFAP2A was higher in ovarian cancer cell lines than in FE25, which was consistent with the predicted results above." (PMID 38265973, 2024). "It was observed that DLEU1 is under-expressed in ovarian cancer and regulates TFAP2A expression via miR-429, thereby suppressing tumorigenesis." (PMID 34740384, 2021). "Significant differences between control and ovarian cancer tissues were seen for the expression of the TFAP2A gene, and was higher in case of ovarian cancer tissue (p < 0.001)." (PMID 31362717, 2019). "Furthermore, in the CCLE database, the expression levels of BUB1B, NDC80, ELF3, TFAP2A and hsa-miR-655 were confirmed among different ovarian cancer cell lines." (PMID 33493131, 2021). "Moreover, the protein levels of EIF3 and TFAP2A were significantly higher in ovary cancer tissues than in normal ovary tissues based on HPA database." (PMID 33493131, 2021). "In ovarian cancers increased expression of human chorionic gonadotropin beta subunit is associated with demethylation of CGB promoter regions and CGB3–9 expression level strongly correlates with expression of TFAP2A transcription factor." (PMID 31362717, 2019). "Indeed, the results of the present study showed that, similar to the placenta, the expression of CGB genes in ovarian cancer strongly correlates with TFAP2A expression." (PMID 31362717, 2019). "TFAP2A is closely related to the process of regulating the cell cycle, epithelial-mesenchymal transition and apoptosis and can participate in regulating the proliferation and migration of cervical cancer, ovarian cancer and other tumor cells and promote the occurrence and development of tumors." (PMID 35739589, 2022). "In ovarian cancer CGB expression positively correlated with TFAP2A transcripts level and expression of TFAP2A transcription factor was significantly higher in cancer than in control tissues." (PMID 31362717, 2019). "Overexpression of TFAP2A and ERBB2 was observed on the mRNA level in relation to other ovarian cancer subtypes." (PMID 28611940, 2017). "Besides, we conducted Western blot to check the constitutive expression of TFAP2A in normal ovarian epithelial cell line FE25 and ovarian cancer cell lines such as 8910, OVCAR3, A2780, and SKOV3." (PMID 38265973, 2024). "Meanwhile, in the GRN analysis for core genes and EMT regulators, it was also found that TFAP2A and hsa-miR-655 could exert a crucial function in the EMT modulation of ovarian cancer." (PMID 33493131, 2021).
glioma (6 papers, 2017 to 2023). A benign or malignant brain and spinal cord tumor that arises from glial cells (astrocytes, oligodendrocytes, ependymal cells). "In glioma, TFAP2A disturbs the expression of stemness-related genes, such as NANOG, SOX2 and CD133, via both directly binding the regulation region of NANOG and indirectly interfering with the IL6/JAK2/STAT3 signaling pathway." (PMID 37291585, 2023). "The combination treatment increased Tfap2a expression and improved Cd8+ T-cell abundance, indicating the combined efficacy against gliomas." (PMID 37330579, 2023). "On the other hand, TFAP2A, B genes, known tumor suppressor genes, participate in the reduction of glioma progression, by downregulation of Bcl-xl, Bcl-2, c-IAP2, and survivin." (PMID 29119102, 2017). "Furthermore, exosomes from the hypoxic microenvironment, as well as miR-1246 and miR-10b-5p, target TFAP2A in normoxic glioma cells to promote angiogenesis and oncogenesis." (PMID 37291585, 2023). "Noteworthy, Decitabine upregulated Pdl1 expression even other gene expression in gliomas, but Tfap2a overexpression could downregulate Decitabine-induced Pdl1 upregulation, elucidating the AP-2α methylation and AP-2α-suppressed PD-L1 expression in certain types of gliomas." (PMID 37330579, 2023). "Besides, miR-10b-5p-enriched exosomes were then internalized by normoxia glioma cells to enhance the migration and invasion of glioma through suppressing fyn-related kinase (FPK) and Transcription factor AP-2 alpha (TFAP2A), respectively." (PMID 35095909, 2021).
colon cancer (5 papers, 2017 to 2025). "The TFAP2A gene encodes activated protein 2α (AP-2α), a tumor suppressor implicated in the transcriptional control of colon cancer." (PMID 40896696, 2025). "Activated protein 2α (AP-2α) encodes a tumor suppressor by TFAP2A, which regulates colon cancer transcription." (PMID 37020597, 2023). "It is almost consistent with the prediction of bioinformatic results that the levels of TFAP2A and PD-L1 protein were upregulated in three out of four colonic cancer tissues." (PMID 38265973, 2024). "TFAP2A protein level was upregulated in fresh colon tumor tissue samples compared to that in the adjacent normal tissues, which essentially positively correlated with the expression of PD-L1." (PMID 38265973, 2024). "Previous studies in breast and colon cancer indicated that the effect of SUMO inhibition on CD44 expression was dependent upon TFAP2A." (PMID 29383121, 2017). "SUMO-conjugated TFAP2A was identified as a protein of approximately 55kD and is consistent with findings previously reported in breast and colon cancer cell lines." (PMID 29383121, 2017). "Becket al. used CRISPR/Cas9 and short hairpin RNA to eliminate TFAP2A expression in HCT116 and a group of colon cancer cell lines." (PMID 37020597, 2023).
gallbladder carcinoma (5 papers, 2022 to 2025). "Furthermore, TFAP2A was upregulated in gallbladder carcinoma, promoting the increase of Fe2+ and malondialdehyde levels, and TFAP2A silencing attenuated the expression of key genes associated with oxidative stress." (PMID 38178888, 2023). "More recent research using bioinformatics analysis and microarray data of differentially expressed genes (DEGs), identified transcription factor AP-2 alpha (TFAP2A) as a mediator of ferroptosis via Nrf2 pathways in gallbladder carcinoma." (PMID 41470866, 2025). "Additionally, suppression of TFAP2A inhibited cell proliferation, migration and invasion via initiating oxidative stress and ferroptosis in gallbladder carcinoma." (PMID 37064095, 2023). "NADPH levels in gallbladder cancer cells were significantly reduced after inhibition of TFAP2A." (PMID 35494004, 2022). "Notably, it has been reported that TFAP2A regulates iron death in gallbladder cancer cells by activating the NRF2 pathway." (PMID 35494004, 2022). "In addition, it has been suggested that TFAP2A can regulate the ferroptosis of gallbladder cancer cells through the Nrf2 signaling axis, so TFAP2A may act as a regulatory factor of ferroptosis." (PMID 36881404, 2023).
Char syndrome (4 papers, 2016 to 2024). Char syndrome is characterized by the triad of patent ductus arteriosus (PDA), facial dysmorphism and hand anomalies. "The mutation in the aptf-2(qm27) allele lies in the basic region of the DNA binding domain, a region that was defined as a mutation hotspot for BOFS and Char Syndorme in the human TFAP2A and TFAP2B genes." (PMID 27176626, 2016).
lymph node metastasis (4 papers, 2021 to 2024). "In addition, univariate and multivariate analyses of OS revealed that TFAP2A level, tumour differentiation, tumour stage and lymph node metastasis were independent risk factors." (PMID 39695171, 2024). "Moreover, TFAP2A level, tumour diameter, tumour differentiation, tumour stage and lymph node metastasis were independent risk factors related to DFS." (PMID 39695171, 2024). "However, analysis showed that lymph node metastasis may be significantly associated with high expression of TFAP2A, TFAP2C, and TFAP2E." (PMID 37859819, 2023). "Additionally, we also confirmed the cancer-regulating function of miR-16 family/TFAP2A/PSG9 axis in LUAD clinical specimens, especially for lymph node metastasis." (PMID 33824285, 2021).
non-small cell lung carcinoma (4 papers, 2018 to 2026). A group of at least three distinct histological types of lung cancer, including non-small cell squamous cell carcinoma, adenocarcinoma, and large cell carcinoma. "Survival analysis demonstrated that elevated TFAP2A expression correlates with poorer overall survival, suggesting its potential as a prognostic marker in non-small cell lung cancer." (PMID 41438579, 2026).
Obesity (4 papers, 2014 to 2025). Accumulation of substantial excess body fat. "The related genes of obesity (ADIPOQ, GCG, PCSK1N, TFAP2A, and PYY) were also found to play significant roles in the occurrence of some types of cancer (BRCA, COAD, and UCEC)." (PMID 33299884, 2020). "This suggests that the deletion of Tfap2a in hepatocytes does not lead to obesity, but affects the lipid metabolism pathway of the liver." (PMID 40180937, 2025). "In addition, five related genes of obesity (ADIPOQ, GCG, PCSK1N, TFAP2A, and PYY) were distributed in the top 25 over/underexpressed genes of cancer tissues." (PMID 33299884, 2020).
orofacial clefting (4 papers, 2011 to 2024). "In contrast, targeting Tfap2a in the surface ectoderm in the region of the face associated with the lens placode causes a mild form of orofacial clefting." (PMID 35333176, 2022). "TFAP2A has also been linked to non-syndromic orofacial clefting (MIM 119530)." (PMID 35333176, 2022). "Here, we have shown that, as the level of functional Tfap2a transcripts are decreased, presumably below a certain threshold, there are changes in Fgf signaling, prominence growth and facial shape that are associated with orofacial clefting." (PMID 25381013, 2015). "Further studies are warranted to determine the mechanistic links between Tfap2a and Fgf signaling as well as a possible wider role for variance in facial shape and orofacial clefting." (PMID 25381013, 2015). "While this gene does not appear to be directly disrupted by chromosomal breaks in the three affected subjects, Tfap2a knockout mice exhibit pleiotropic morphological abnormalities, including orofacial cleft." (PMID 22242126, 2011). "We therefore investigated whether alterations in Tfap2a could also influence phenotypic variance as a potential mechanism for interactions with Fgf8 gene dosage in modifying orofacial clefting." (PMID 25381013, 2015). "Moreover, recent analyses have identified mutations in TFAP2A as the cause of human BOFS, which is characterized in part by orofacial clefts of varying severity." (PMID 25381013, 2015). "Furthermore, these results indicate that AP-2α has the most potent TF activity since mice lacking Tfap2b, but containing one functional copy of Tfap2a, can still undergo normal facial development, whereas the reverse results in orofacial clefting." (PMID 35333176, 2022).
prostate carcinoma (4 papers, 2011 to 2023). A carcinoma that arises from epithelial cells of the prostate gland. "In prostate cancer, TFAP2A can bind to the ESR2 promoter region to activate expression." (PMID 37291585, 2023). "Notably, TFAP2A also exerts anti-angiogenesis effects in different tissues (inhibitory effects in prostate cancer)." (PMID 37291585, 2023).
anaplastic thyroid cancer (3 papers, 2017 to 2024). "The sumoylation of TFAP2A results in altered patterns of gene expression associated with anaplastic thyroid cancer." (PMID 35406382, 2022). "Recent findings indicate that the progression from papillary to anaplastic thyroid cancer in cell models may be driven by the SUMOylation of transcription factor TFAP2A, which alters gene expression patterns linked to anaplastic thyroid cancer." (PMID 39457720, 2024). "The results from recent experiments in anaplastic thyroid cancer cell lines suggest that the dedifferentiation of papillary thyroid cancer into anaplastic thyroid cancer is caused at least in part by the sumoylation of the transcription factor TFAP2A." (PMID 35406382, 2022).
breast tumor (3 papers, 2008 to 2017). "Remarkably, in a large panel of breast tumor datasets originating from more than 1500 patients, the expression of TFAP2A mRNA is also downregulated in the basal sub-type cancer category." (PMID 28412966, 2017). "Expression levels of four TFAP2A isoforms were assayed at the level of RNA and protein (via the generation of isoform-specific antibodies) in a panel of breast tumour cell lines and in tissue from normal breast and primary tumour samples." (PMID 21375726, 2011). "IH data were available for CDH1, TFAP2A, and RBP4 proteins; and only data from antibodies exhibiting differential expression among breast tumors were reported herein." (PMID 19116033, 2008).
cleft lip (3 papers, 2021 to 2024). Congenital defect in the upper lip where the maxillary prominence fails to merge with the merged medial nasal prominences. "In a study about patients with nonsyndromic cleft lip and palate, Single-nucleotide variants (SNVs) were identified on TFAP2A in the non-coding region." (PMID 38265973, 2024). "Mutations in the TFAP2A gene usually lead to cleft lip in the middle eye and cause branch ocular facial syndrome." (PMID 33717678, 2021). "By describing a case of a unique TFAP2A gene mutation that caused neonatal BOFS and reviewing the pertinent literature, we discovered that the majority of neonatal BOFS cases presented with cleft lip, branchial skin abnormalities, and eye deformities, as well as multiple genetic variations." (PMID 37932997, 2023).
gout (3 papers, 2017 to 2025). A condition characterized by painful swelling of the joints, which is caused by deposition of urate crystals. "Through experiments both in vitro and in vivo, we demonstrated that increased NRBP1 expression in gout patients may be regulated through methylation-dependent binding of TFAP2A to the B1 region, 72 bp upstream of NRBP1 transcription start site." (PMID 28932319, 2017). "This study found that hypomethylation of the NRBP1 promoter region reduces the binding of NRBP1 to the transcription factor TFAP2A, which leads to elevated levels of NRBP1 and may contribute to the development of gout." (PMID 39734218, 2024). "Hypomethylation at the promoter region of NRBP1 reduces the binding of TFAP2A and thus leads to elevated NRBP1 expression, which might contribute to the development of gout." (PMID 28932319, 2017). "DNA methylation increases the binding of transcription factor TFAP2A to B1, leading to suppressed gene expression; low methylation in the NRBP1 promoter region reduces TFAP2A binding, thereby increasing NRBP1 expression, which may contribute to the development of gout." (PMID 41311848, 2025).
hepatocellular carcinoma (3 papers, 2010 to 2025). A malignant tumor that arises from hepatocytes. "In hepatocellular carcinoma, TFAP2A is a key player in the transcriptional regulation of a cluster of DNA damage repair genes: DNA repair is prevented by TFAP2A depletion, and the new TFAP2A inhibitor LEI110 shows anti-tumour efficacy in HCC cell lines." (PMID 38503825, 2024).
liver cancer (3 papers, 2019 to 2025). An epithelial or non-epithelial malignant neoplasm that arises from the liver. "We wondered whether the deletion of Tfap2a in hepatocytes promotes primary liver cancer by affecting metabolism." (PMID 40180937, 2025). "Not only the hub elements, but it is noteworthy that the extracted subnetworks such as the miR-214 and TFAP2A may shed the light on the importance of the sumoylation pathway in maintenance of the hepatic cancer stemness." (PMID 30944375, 2019). "In our study, AOC1 abolished sh-TFAP2A-regulated inhibition of macrophage M2 polarization, which was consistent with the previous finding that TFAP2A could enhance M2 polarization of macrophages in liver cancer." (PMID 40813717, 2025).
squamous cell carcinoma (3 papers, 2018 to 2023). A carcinoma arising from squamous epithelial cells. "The analysis of the TFAP2A gene expression level in relation to the clinicopathological characteristics of squamous cell carcinoma patients showed a statistically significant correlation only with regard to smoking status." (PMID 36831334, 2023). "The analysis of tumor differentiation shows that TFAP2A and TFAP2C are closely related to the differentiation of BLCA into basal/squamous cell carcinoma." (PMID 37859819, 2023).
cholangiocarcinoma (2 papers, 2023 to 2025). A carcinoma that arises from the intrahepatic biliary tree (intrahepatic cholangiocarcinoma) or from the junction, or adjacent to the junction, of the right and left hepatic ducts (hilar cholangiocarcinoma). "For instance, in cholangiocarcinoma cells, TNFα induces increased accessibility of the TFAP2A promoter, while it is reduced in gallbladder cancer cells." (PMID 37291585, 2023). "It has been reported that TFAP2A can be involved in the EMT process in multiple ways, for example, by binding of TFAP2A to the TGFB1 promoter in HCCC cholangiocarcinoma cell lines." (PMID 39994865, 2025).
congenital cataract (2 papers, 2016 to 2020). "We identified a ~98-kb homozygous deletion involving several exons of GCNT2 and the region upstream of TFAP2A in two children affected with congenital cataracts from a consanguineous family of Pakistani decent." (PMID 27609212, 2016).
cutaneous melanoma (2 papers, 2000 to 2024). A primary melanoma arising from atypical melanocytes in the skin. "In addition to ovarian serous carcinomas, more than 4% of esophageal carcinoma, skin cutaneous melanoma, uterine corpus endometrial carcinoma, diffuse large B-cell lymphoma, and bladder urothelial carcinoma obtained TFAP2A gene alteration." (PMID 38265973, 2024). "This chromosome region is thus suggestive of harbouring a putative tumour suppressor gene of cutaneous melanoma, but this referring specifically to TFAP2A could not be completely verified in this analysis." (PMID 10864211, 2000).
ductal carcinoma in situ (2 papers, 2013 to 2022). "TFAP2A encodes the AP-2α transcription factor that is normally expressed in breast ductal epithelium nuclei, with progressive expression loss from normal, to ductal carcinoma in situ, to invasive cancer." (PMID 23544012, 2013). "In invasive breast cancer, TFAP2A levels were established to be lower, compared to normal breast and ductal carcinoma in situ." (PMID 35494004, 2022).
head and neck squamous cell carcinoma (2 papers, 2022 to 2023). A squamous cell carcinoma that arises from any of the following anatomic sites: lip and oral cavity, nasal cavity, paranasal sinuses, pharynx, larynx, and salivary glands. "For example, Linc00467 acts as a ceRNA to adsorb miR-1285-3p to mediate TFAP2A expression in head and neck squamous cell carcinoma (HNSCC)." (PMID 37291585, 2023). "For example, in head and neck squamous cell carcinoma, LINC00467 regulates transcription factor AP-2 alpha (TFAP2A) expression as a ceRNA by adsorbing microRNA-1285-3p, thus inducing invasive changes in the tumor and inhibiting the apoptosis of cancer cells." (PMID 35587748, 2022).
lung squamous cell carcinoma (2 papers, 2018 to 2026). "GDNF and TFAP2A have been reported to be highly methylated in squamous cell carcinoma of the lung and in adenocarcinoma, respectively." (PMID 29796116, 2018).
metastatic tumors (2 papers, 2017 to 2024). "Genes that were up-regulated in primary and metastatic tumors included SETD5 (SET domain containing 5) and TFAP2A (transcription factor AP-2 alpha)." (PMID 28086829, 2017). "Firstly, we performed the TF enrichment analysis between primary tumors and metastatic tumors, and finally, seven TFs were identified as differentially expressed TFs, including CBX2, CDX2, FOXA2, KLF4, NANOG, NCAPG, and TFAP2A, which was demonstrated in a heatmap and a volcano plot." (PMID 38702698, 2024).
myopia (2 papers, 2018 to 2022). "On the one hand, the results of Metascape revealed a potential role of TF in the development of myopia with the enrichment of Smad6, NrOb2, Gtf2i, Tfap2a, Pax7, Pax6, Sox9 and Smad3." (PMID 34841657, 2022).
neuroblastoma (2 papers, 2020 to 2023). Neuroblastoma (NB) is the most common solid, extracranial childhood tumor. "In neuroblastoma, the expression of TFAP2A is related to poor differentiation and advanced tumor stage." (PMID 37291585, 2023).